CLDN5 (claudin 5)
Diseases named in the same sentence as CLDN5 in open-access papers (continued):
Sharing a sentence is not in itself a finding about the gene and the disease.
glioblastoma (8 papers, 2012 to 2025). The most malignant astrocytic tumor (WHO grade IV). "Claudin-5 can interact with claudin-3 and the selective loss of the latter during autoimmune encephalomyelitis or human glioblastoma is associated with BBB breakdown." (PMID 23140302, 2012). "Taken together, zonulin prevents claudin-5 from maintaining a functional blood–brain axis, serving as a putative mechanism in glioblastoma carcinogenesis." (PMID 39200114, 2024). "Significant upregulation of CLDN5 was observed in the following five tumors: glioblastoma multiforme (GBM), brain lower-grade glioma (LGG), liver hepatocellular carcinoma (LIHC), pancreatic adenocarcinoma (PAAD), and pheochromocytoma and paraganglioma (PCPG)." (PMID 37286335, 2023). "As Occludin and Claudin-5 are the anchors of transendothelial cell permeability, the mechanism by which glioblastoma U-87 cells decreased the resistance of the bEnd.3 monolayer was investigated in the current study." (PMID 35053392, 2022). "We showed a significant decreasing of Dkk-3 and claudin-5 in human glioblastoma cell lines, as well as in U-87 MG xenograft tumors and in glioblastoma human patient’s tissues, with an involvement of the apoptosis process." (PMID 30680070, 2018). "SFN-Cys may disrupt microtubules, modulate mitophagy, and alter the expression of S100A4 and Claudin-5 to inhibit migration and invasion in glioblastoma (GBM) cells." (PMID 40597933, 2025). "In accordance with the essential role of claudin-5 in preserving the integrity of the BBB, a decrease in claudin-5 expression increases BBB permeability, abnormal neoangiogenesis, and progression in glioblastomas." (PMID 39200114, 2024). "In the present study we investigated the expression of Dkk-3, claudin-5, apoptosis markers and TLR-4 receptor protein levels in in vitro studies on U-138MG, A-172, LN-18 and LN-229 human glioblastoma cell lines, and in vivo study using TLR-4 KO mice and in glioblastoma human patient’s tissues." (PMID 30680070, 2018).
Hyperglycemia (8 papers, 2014 to 2025). An increased concentration of glucose in the blood. "Our data showed that the levels of occludin and claudin-5 obviously decreased 1d after injury, and hyperglycemia significantly aggravated these reductions, along with those of p120 and β-catenin, both in vivo and in vitro." (PMID 28794417, 2017). "Experimental evidence demonstrates that hyperglycemia and pro-inflammatory cytokines synergistically degrade these junctional complexes, particularly through the downregulation of Cldn5 (essential for barrier selectivity) and Ocln (critical for junction assembly)." (PMID 40244194, 2025). "However, in hCMEC/D3 cells, hypoglycemia significantly decreased claudin-5 expression but hyperglycemia increased VE-cadherin expression." (PMID 39475379, 2024). "In retinal endothelial cells, hyperglycemia remarkably reduced claudin-5 expression (but not VE-cadherin)." (PMID 39475379, 2024). "In addition, APN deficiency resulted in severe vascular permeability under relatively short-term hyperglycemia, together with a significant increase in vascular cellular adhesion molecule-1 (VCAM-1) and a reduction in claudin-5 in the retinal endothelium." (PMID 35264685, 2022). "Our data demonstrate a progressive down-regulation of claudin-5 expression at cell-cell contacts following hypoglycemic exposure, while exposure to hyperglycemia did not alter its immunoreactivity, in accordance with previous reports." (PMID 24708805, 2014). "Compared to controls, exposure to hypoglycemia (3 and 24h) down-regulated the expression of claudin-5 and disrupted the ZO-1 localization at cell-cell contacts, while hyperglycemia marginally reduced claudin-5 expression without affecting ZO-1 distribution." (PMID 24708805, 2014).
cerebral infarction (7 papers, 2015 to 2026). An ischemic condition of the brain, producing a persistent focal neurological deficit in the area of distribution of the cerebral arteries. "MMP-2/MMP-9 aggravates BBB dysfunction caused by cerebral infarction by degrading ZO-1 and claudin-5, all TJ proteins." (PMID 33584203, 2020). "In general, we concluded that ROS-accumulation-mediated inflammatory pathway activation underlies microvessel endothelial cell destruction during cerebral infarction, and protection of claudin 5 stability is an important strategy to improve cerebrovascular integrity." (PMID 35892657, 2022). "To determine whether GSH reduces the extent of cerebral infarction, cell death after ischemia, and reperfusion injury, we measured infarct size in ischemic brain tissue and the expression of claudin-5 associated with brain infarct formation." (PMID 25722793, 2015). "Both kinds of EVs exerted similar efficacies in reducing the cerebral infarction volume and BBB leakage and enhancing the expressions of ZO-1 and Claudin-5 after 24 h pMCAo in rats." (PMID 36855156, 2023). "At the same time, Claudin-5 and occludin were degraded by MMP2, the BBB was destroyed and the size of cerebral infarction increased." (PMID 35959401, 2022). "The evaluation included measures such as neurological deficit score (NDS), percentage of cerebral infarction volume, brain water content, inflammation-related factors, oxidative stress-related indicators, apoptosis indicators (caspase-3), and blood-brain barrier (BBB) permeability (Claudin-5)." (PMID 38545549, 2024).
Crohn disease (7 papers, 2019 to 2025). A gastrointestinal disorder characterized by chronic inflammation involving all layers of the intestinal wall, noncaseating granulomas affecting the intestinal wall and regional lymph nodes, and transmural fibrosis. "In line with our results, various colonic conditions such as acute colitis and Crohn's disease have also found decreased expression of claudin-5 associated with increased Bacteroides abundance." (PMID 36387539, 2022). "Claudin-5 redistribution was also found in colon biopsies of patients with Crohn’s disease or lymphocytic colitis and was mimicked by TNFα and IFNγ in colon epithelial cell lines in vitro." (PMID 40438590, 2025). "Downregulation and redistribution of claudin-8 along with claudin-5 lead to alterations in tight junction’s structure and pronounced barrier dysfunction both in mild and moderately active Crohn’s disease." (PMID 33364202, 2020). "Claudin-5 and -8 are also reduced and redistributed in Crohn’s disease, which is characterized by intestinal inflammation and diarrhea." (PMID 31717457, 2019).
lung adenocarcinoma (7 papers, 2009 to 2025). A carcinoma that arises from the lung and is characterized by the presence of malignant glandular epithelial cells. "For instance, overexpression of Cldn5 in human brain endothelial cells significantly reduced A549 lung adenocarcinoma cell transmigration across an endothelial monolayer in vitro." (PMID 40940757, 2025). "Tissue microarray assay in human lung adenocarcinoma and lung squamous carcinoma showed that Claudin-5 was weakly stained in adjacent tissues, whereas darkly stained in tumor tissues, but Claudin-7 staining showed the opposite results." (PMID 30874545, 2019). "Moreover, overexpressed CLDN5 reduced the paracellular permeability of hCMEC/D3 cells and decreased the invasion of lung adenocarcinoma A549 cells." (PMID 33714203, 2021). "Mutations in CLDN5 may cause velocardiofacial syndrome, whereas mutations in CLDN18 are related to lung adenocarcinomas." (PMID 23741331, 2013). "We found Cldn5 (claudin 5) to be significantly repressed in lung adenocarcinoma." (PMID 19812696, 2009). "Notably, claudin 2 was selectively expressed in lung adenocarcinomas, whereas claudin 5 expression was strongly repressed in lung tumors." (PMID 19812696, 2009). "Conversely, increasing the expression of Claudin-5 (CLDN5) in brain endothelial cells can reduce paracellular permeability and the migration of lung adenocarcinoma A549 cells across the BBB." (PMID 39408656, 2024). "Reinforced expression of CLDN5 enhances BBB integrity and hinders invasion of lung adenocarcinoma A549 cells." (PMID 33262947, 2020).
ovarian carcinoma (7 papers, 2013 to 2023). A malignant neoplasm originating from the surface ovarian epithelium. "In other pathological circumstances such as anthrax infection or ovarian cancer, pleural and peritoneal effusion is associated with endothelium disruption and down-regulation of claudin-5 expression." (PMID 32405335, 2020). "The researchers also established a co-culture system of both ovarian cancer cells and endothelial cells to examine whether a functional association exists between claudin-5 and increased peritoneal permeability." (PMID 23685873, 2013). "SIRT1 and KLF4 inhibit the migration and invasion of ovarian cancer cells by activating the transcription of CLDN5." (PMID 37286335, 2023). "Based on these data, we assumed a functional role of VEGF-dependent regulation of VE-cadherin and claudin 5 concerning regulation of endothelial permeability also in the peritoneal tissue of ovarian cancer patients." (PMID 26868378, 2016). "Since it has been shown in vivo that the adhesion proteins VE-cadherin and claudin 5 are reduced in the peritoneal vessels of ovarian cancer patients, we measured the production of VE-cadherin and claudin 5 in HUVEC grown in the co-culture system in vitro." (PMID 26868378, 2016). "As we had already demonstrated a significant reduction for claudin 5 levels in the peritoneal vessels of ovarian cancer patients as compared to the controls in a former study we here performed an analysis on the level of gene expression." (PMID 26868378, 2016). "In summary, our results demonstrate that VEGF plays an important role in pathological hyperpermeability and ascites formation of human ovarian cancer via down-regulation of a cascade of adhesion proteins (VE-cadherin and subsequent claudin 5)." (PMID 26868378, 2016). "The results showed that the serum and ascites of preoperative ovarian cancer patients had increased levels of VEGF and that there was a VEGF-dependent decrease of claudin-5 in endothelial cells co-cultured with ovarian cancer cells." (PMID 23685873, 2013). "Interest in the expression of claudin-5 and its correlation with ovarian cancer behavior also arose." (PMID 23685873, 2013). "The ovarian cancer patients had a lower amount of claudin-5 detected in the peritoneal vessels compared to healthy controls." (PMID 23685873, 2013). "The role of VEGF-dependent production of claudin-5 as a regulator of vascular permeability in ovarian cancer patients was thus investigated by studying the amount claudin-5 in peritoneal tissue as well as VEGF in serum and ascites." (PMID 23685873, 2013). "Furthermore, three genes showed low expression in the ovarian cancer samples compared with normal tissue samples and included CLDN5, CLDN11, and CLDN15." (PMID 34249076, 2021). "Furthermore, dismantling of VEC clusters during pathological angiogenesis in human ovarian carcinomas is accompanied by the downregulation of Claudin-5 and VE-PTP." (PMID 29233846, 2018). "Moreover, we simulated the in vivo situation for the first time in a co-culture model with human ovarian cancer cells extracted from ovarian cancer patients of our department, and investigated the changes of VE-cadherin and claudin 5 after VEGF inhibition." (PMID 26868378, 2016). "Here, we investigated the molecular regulation of endothelial permeability by the vascular endothelial growth factor (VEGF) and both tight and adherens junction proteins (VE-cadherin and claudin 5) with regards to the tumor biology of different ovarian cancer types." (PMID 26868378, 2016). "Confirming the results of our previous studies in a co-culture model with synthesized Ovcar-3 cells we found a significant (p < 0.05) decrease of claudin 5 in HUVEC co-cultured with our human ovarian cancer cells, which was prevented by simultaneous treatment with the VEGF-inhibitor Flt1-Fc." (PMID 26868378, 2016).
ovarian carcinoma (continued). "The results suggest that one mechanism by which VEGF may induce ascites formation in ovarian cancer patients is by increasing peritoneal permeability secondary to the downregulation of the TJ protein claudin-5 in the peritoneal endothelium." (PMID 23685873, 2013). "The down regulation of adherens junctions (VE-cadherin) and subsequent suppression of tight junctions (claudin 5) by VEGF, which is accumulated in serum and ascites, may account for the massive loss of fluid into the abdominal cavity in advanced ovarian cancer." (PMID 26868378, 2016). "In pathological angiogenesis of human ovarian carcinomas, reduced VEC expression paralleled decreased levels of claudin-5 and VE-PTP." (PMID 29233846, 2018). "In vessels of human ovarian carcinomas, downregulation of VEC parallels reduced Claudin-5 and VE-PTP expression, pointing at a possible involvement of the identified mechanism." (PMID 29233846, 2018). "Furthermore, human primary ovarian cancer cells were co-cultured with human umbilical vein endothelial cells (HUVEC) and changes in VE-cadherin and claudin 5 were investigated after VEGF inhibition." (PMID 26868378, 2016).
brain tumor (6 papers, 2017 to 2025). "To extend these in vitro findings, we stained brain tumor sections for ZO-1 and Cldn5, another tight junctional protein." (PMID 40408475, 2025). "Both ZO-1 and Claudin-5 structures were damaged in the brain tumor vasculature as compared to the control brain." (PMID 35351947, 2022). "Metastatic brain tumors are known to have a disrupted inter-endothelial tight junction due to the downregulation of tight junction components, including claudin-1, claudin-5, and occludin." (PMID 34722268, 2021).
hepatocellular carcinoma (6 papers, 2012 to 2025). A malignant tumor that arises from hepatocytes. "In the context of liver cancer, Cldn5 expression has been investigated in hepatocellular carcinoma (HCC)." (PMID 40940757, 2025). "Previously, Sakaguchi and colleagues also demonstrated heterogeneous Claudin-5 expression in tumoral endothelium of hepatocellular carcinoma and surrounding LSECs depending on fibrotic grade and tumor differentiation." (PMID 22509281, 2012). "Regarding TJ molecules, LSECs of nontumorous areas in samples of human hepatocellular carcinoma were shown to contain claudin-5, the typical transmembrane component of TJ in vascular endothelium." (PMID 22509281, 2012).
melanoma (6 papers, 2011 to 2023). A malignant, usually aggressive tumor composed of atypical, neoplastic melanocytes. "The claudin-5 signal was strongly decreased by both melanoma cell lines in RBECs and disappeared completely from D3 cells, while melanoma conditioned media induced a less pronounced effect." (PMID 21674054, 2011). "Moreover melanoma cells in contact with BECs disrupt the integrity of the BBB by degrading the tight junctional proteins (claudin-5 and ZO-1)." (PMID 37190188, 2023). "Some of these include Dead H box helicase 11 (DDX11), Claudin 5 (CLDN5), chemokine CXC motif (CXCL1 ligand 1, melanoma growth), glutathione S-transferase mu 1 (GSTM1), major histocompatibility complex class I K (HLA-K), and thrombospondin 1 (THBS1)." (PMID 36769056, 2023). "Immunofluorescent staining illustrated that the CD31 (marker of blood vessels) coverage was lower after JP1 treatment; however, the α-SMA (marker of mural cells), claudin 5 (marker of endothelial cells), and desmin (marker of pericytes) coverage was higher after JP1 treatment in melanoma." (PMID 37192004, 2023). "Similarly, researchers found that melanoma cell lines cultured in activated conditioned media induce this transitional process (a TGF-β-dependent manner) in the BEC, as was demonstrated by a reduced expression of claudin-5 and VE-cadherin, and increased expression of fibronectin and SMA." (PMID 37190188, 2023).
cardiomyopathy (5 papers, 2016 to 2025). A disease of the heart muscle or myocardium proper. "This was achieved following a single administration of a recombinant adeno-associated viral vector (AAV6) containing a mouse claudin-5 expression cassette under the control of the minimal cytomegalovirus promoter to the hearts of mice with cardiomyopathy." (PMID 30691500, 2019). "Notably, adenovirus-mediated Cldn5 overexpression (rAAV6-Cldn5 dko) in this model for 4 weeks inhibited hallmark features of cardiomyopathy and improved histological indicators of cardiac injury." (PMID 40940757, 2025). "Supporting this, Cldn5 was significantly downregulated at the cardiomyocyte lateral membrane in a dystrophin–utrophin double knockout (Dmdmdx;Utrn−/− dko) mouse model that recapitulates features of cardiomyocyte degeneration and myocarditis, implicating Cldn5 loss in cardiomyopathy pathogenesis." (PMID 40940757, 2025). "In addition, we used this model to test whether claudin-5 may represent a therapeutic target for additional forms of muscular dystrophy associated cardiomyopathy." (PMID 27999547, 2016). "In the Dystrophin−/− (Dmd1)/Utrophin−/− (Utrn) cardiomyopathy model, Cldn5 mRNA and protein levels decline; in contrast, Cldn5 overexpression diminishes cardiomyopathy in Dmd1−/−:Utrn−/− mice." (PMID 31174463, 2019). "Restoration of claudin-5 levels prevented the physiological hallmarks of cardiomyopathy and improved histological outcome." (PMID 30691500, 2019). "In a mouse model of cardiomyopathy and muscular dystrophy, claudin-5 levels are drastically reduced." (PMID 30691500, 2019). "Consistently, Cldn5 levels were downregulated in human heart tissues from patients with ventricular dysfunction caused by both ischemic and non-ischemic cardiomyopathies, compared to healthy controls." (PMID 40940757, 2025). "Thus, it can be assumed that the decrease of claudin-5 level occurs before the onset of damage to the heart, and that the stable expression of claudin-5 in the mouse model prevents the occurrence of cardiomyopathy." (PMID 36408244, 2022). "Claudin-5 transcript and protein levels are reduced at a very early stage of the disease, and sustained expression of claudin-5 in this model is able to prevent the onset of cardiomyopathy." (PMID 36408244, 2022).
Hypertension (5 papers, 2020 to 2026). The presence of chronic increased pressure in the systemic arterial system. "In contrast, expression of claudin-5 was reduced in stroke-prone SHR and the two-kidney, two-clip model of hypertension, however, the role of ANG II was not investigated in these studies." (PMID 41602155, 2026).